S100A9 (S100 calcium binding protein A9)
Diseases named in the same sentence as S100A9 in open-access papers (continued):
Sharing a sentence is not in itself a finding about the gene and the disease.
breast carcinoma (86 papers, 2005 to 2025). "Overexpression of S100A9 has been implicated in the development and progression of many cancer types, including breast cancer, and correlated with high expression of Ki67 and HER2." (PMID 39268460, 2024). "Overexpression of the S100A9 protein has been linked to poor prognosis in non-small cell lung cancer, renal cell carcinoma, hepatocellular carcinoma and breast cancer." (PMID 38110349, 2023). "Emerging evidence suggests that benzyl butyl phthalate (BBP) induces expression and secretion of S100A9 in tumor microenvironment cells of breast cancer including tumor‐associated dendritic cells and tumor infiltrating myeloid-derived suppressor cells." (PMID 35484101, 2022). "Activation of S100A9 is also associated with breast cancer metastatic progression, whereas KRT17 is a potent oncogene." (PMID 28886030, 2017). "Higher levels of MMP-9, S100A8 and S100A9 transcripts were each significantly associated with worse relapse-free survival over a 20-year interval when all breast cancers were considered." (PMID 25633981, 2015). "Thus, we believe that further experiments will help to elucidate the underlying mechanism(s) of S100A8 and S100A9 proteins in treatment-resistant ER+ breast cancer." (PMID 39057065, 2024). "Previous studies demonstrated that S100A9 is frequently upregulated in breast tumors, and its overexpression is closely associated with metastatic progression, chemoresistance, and poor prognosis of patients with breast cancer." (PMID 35484101, 2022). "In addition, the expression levels of S100A9 are associated with the chemoresistance of breast cancer cells to doxorubicin/cyclophosphamide." (PMID 35484101, 2022). "Additionally, IL-1 receptor-associated kinase 1 (IRAK1) regulates the expression of S100A9 in chromosome 1q21.3-amplified breast cancer cells." (PMID 35484101, 2022). "It has reported that strong expression and secretion of S100A8/S100A9 may be associated with the loss of estrogen receptor in breast cancer, and may be involved in the poor prognosis of Her2+/basal-like subtypes of breast cancer." (PMID 31208368, 2019). "Moreover, S100A9 can induce inflammatory cytokines and is associated with overall survival in ER- PgR- breast cancers." (PMID 27588397, 2016). "The finding of overexpression of a metastasis-associated calcium- and zinc-binding protein encoding gene - S100A9 in CTCs suggests a valid targeting opportunity, demonstrated previously for another member of this family - S100P, in aggressive breast cancer cells." (PMID 22586443, 2012). "S100A8 and S100A9 which form a heterodimer complex 90 are up-regulated in many cancers and have been implicated in the metastatic process including gastric cancer, prostate cancer, colorectal cancer, and breast cancer." (PMID 19691830, 2009). "Moreover, increased S100A9 expression is associated with poor tumor differentiation, poor pathological parameters, high tumor grade, increased tumor recurrence and metastasis, and a poor prognosis of patients with breast cancer." (PMID 35484101, 2022). "Here the authors show that Brca1 deficiency in preclinical breast cancer models is associated with the accumulation of myeloid derived suppressive cells and resistance to immune checkpoint blockade, that could be overcome by targeting S100A9 and CXCL12." (PMID 35304461, 2022). "In patients with lung cancer, breast cancer, or melanoma, S100A9 expression in brain metastases negatively correlated with the benefits of radiotherapy." (PMID 40522460, 2025). "Previous studies have demonstrated that S100A9, FOXC1 and CTGF are involved in the molecular mechanisms underlying organ-specific metastasis in breast cancer." (PMID 40500539, 2025). "They found that adding S100A8 and S100A9 proteins to the MCF7 breast cancer cell line extracellularly promoted cell growth." (PMID 39594999, 2024).
breast carcinoma (continued). "Results showed that ionizing radiation and estrogen affected the expression of those genes that encoded the S100 calcium-binding proteins such as S100P, S100A14, S100A2, S100A8, and S100A9 in the immortalized breast cancer cell line MCF-10F." (PMID 39594999, 2024). "Such authors elucidated the roles of intracellularly produced S100A8 and S100A9 on critical signaling pathways and biological mechanisms responsible for the malignancy of breast cancer." (PMID 39594999, 2024). "Since the S100 protein has been linked to breast cancer invasiveness and metastasis, the S100A8 and S100A9 appeared to reduce breast cancer malignancy by increasing mesenchymal to epithelial transitioning." (PMID 39594999, 2024). "Chronic stress and low social support in breast cancer patients are linked to increased inflammatory signaling and higher S100A8/S100A9 levels, connecting psychological factors with inflammation and metastasis." (PMID 39830522, 2024). "S100A8/S100A9 high mRNA expression was correlated with lower OS in all breast cancer types, especially in Her2 positive and TNBC subtypes." (PMID 39830522, 2024). "The S100A8 and S100A9 members are among the S100 inflammatory proteins shown to modulate several breast cancer processes as progression and malignancy." (PMID 39594999, 2024). "Similar to S100A8, S100A9 expression was significantly upregulated in ER- (P < 0.0001), PR- (P < 0.0001), Her2+ (P = 0.00097) breast cancer." (PMID 38093319, 2023). "For instance, ID1 promoted lung cancer growth by activating CDK4/cyclin D1 and breast cancer metastasis through S100A9 regulation." (PMID 37759448, 2023). "S100A9 is overexpressed in various human cancer types including breast cancer and non-small cell lung cancer, and this overexpression often correlates with a poor prognosis." (PMID 38110349, 2023). "S100A9 expression in human brain metastasis from patients with lung cancer, breast cancer or melanoma negatively correlated with the benefits of radiotherapy." (PMID 37835539, 2023). "The results of pooled analysis showed that both S100A8 and S100A9 mRNA abundances were dramatically upregulated in grade 3 breast cancer tissues in comparison with grade 1–2 cancer tissues." (PMID 38093319, 2023). "Tissue immunofluorescence staining was performed to investigate the distribution of these markers such as En_CXCR4, En_PPP1R1B, and En_S100A9 in breast cancer tissues and the relationship with the position distribution of blood vessels." (PMID 37626402, 2023). "For example, circPFKFB4 inhibits DDB2 degradation in breast cancer and circ_0006156 binds and stabilizes S100A9 in prostate cancer." (PMID 37340423, 2023). "In human breast cancer cells, exogenous S100a9 promotes autophagy through the cell-membrane receptors TLR4 and RAGE." (PMID 37723445, 2023). "In socially isolated animals, the herbal product inhibited IL6/JAK/STAT3 signaling, upregulated OXPHOS signaling, suppressed the expression of RAGE ligands S100a8 and S100a9, and prevented the increase in recurrence of dormant mammary tumors." (PMID 36980301, 2023). "Given the crucial roles of S100A9 in breast cancer progression and therapeutic resistance, understanding how it is regulated is of utmost importance." (PMID 35484101, 2022). "As a secretory cytokine, S100A9 accelerates breast cancer growth and metastasis upon binding to a cell surface receptor, melanoma cell adhesion molecule (MCAM)." (PMID 35484101, 2022). "In terms of S100A9/8, Bergenfelz was the first to report that it can be considered as a novel therapeutic target for patients with ER(−) PgR(−) breast cancers followed by several other studies." (PMID 36536459, 2022). "To validate previous findings that S100A9 promotes breast cancer progression, we first knocked down S100A9 in MDA0MB-231 cells using two independent siRNAs targeting S100A9 (siS100A9 #1 and #2)." (PMID 35484101, 2022).
breast carcinoma (continued). "Elevated levels of S100A8 and S100A9 detected in tear samples from breast cancer patients supports previously reported results indicating elevated levels in serum and tissue of breast cancer patients." (PMID 35471994, 2022). "S100A9 is a calcium binding protein important in the pathogenesis of different cancer types according to previous studies, such as breast cancer, colon adenocarcinoma, hepatocellular carcinoma, etc." (PMID 35760899, 2022). "This study provides a strategy to inhibit the initiation and progression of breast cancer in patients with elevated S100A9 and/or CXCL12 expression." (PMID 35304461, 2022). "S100A8 and S100A9 specifically have been shown to have altered expression levels in breast cancer tissues compared with normal tissues, with increased expression levels associated with non-functional BRCA1 (BReast CAncer gene 1)." (PMID 35471994, 2022). "S100A9 is also upregulated in many cancer types, including breast cancer, colon cancer, hepatocellular carcinoma, gastric cancer, colorectal cancer, non-small-cell lung cancer and cervical cancer." (PMID 34374812, 2022). "Differently, S100A7, S100A8 and S100A9 are co-amplified on chromosome 1q21.3 in breast cancer, have similar functions and cooperate with each other to induce target protein phosphorylation leading to tumor recurrence and chemoresistance." (PMID 35463335, 2022). "Previous research groups have reported that S100A8 and S100A9 were elevated in serum and tissue of breast cancer patients." (PMID 36284356, 2022). "S100A8 and S100A9 had significantly higher expression levels with p-values of 0.0069 and 0.0048 in breast cancer patients, respectively, with an increased fold-change of 7.8 and 10.2 compared to controls." (PMID 35471994, 2022). "This problem can be overridden by combined inhibition of S100A9-CXCL12 signaling with a PD-1 antibody (aPD-1), providing selective strategy for effective immunotherapy in breast cancers with elevated S100A9 and/or CXCL12 protein levels." (PMID 35304461, 2022). "In supporting this notion, higher level expression of S100A9 has poor survival outcomes in breast cancer patients." (PMID 35304461, 2022). "An additional cohort including patients with brain metastases from breast cancer and melanoma reproduced the clinical correlation between S100A9 and radiation response." (PMID 35411077, 2022). "Similar to the observed LC-MS/MS results, S100A8 (p-value <0.0001) and S100A9 (p-value <0.0001) showed significantly higher expression in breast cancer patients." (PMID 35471994, 2022). "Several of the LXRE genes predicted increased regression-free survival in breast cancer subjects, among which Ptgs2, Mfge8, Anxa1, Spp1, S100a9 and Cd14 are biomarkers for MDSC and Treg cells." (PMID 33780491, 2021). "In this study, we evaluated early therapy effects on the TME in syngeneic murine breast cancer via S100A9-specific in vivo imaging." (PMID 33401528, 2021). "In other cancer types, such as lung cancer, prostate cancer, nasopharyngeal carcinoma, and breast cancer, S100A9 is expressed mainly by neoplastic tumor cells themselves." (PMID 34157683, 2021). "TRIM24 activated atherogenesis and cell viability in breast cancer cell lines and S100A9 inhibited the metabolism of amino acids." (PMID 34575874, 2021). "We also examined the S100A8 and S100A9 mRNA levels in normal breast and breast cancer tissues using RNA sequencing data comprised of 65 normal and 68 cancer tissues." (PMID 33446797, 2021). "To further assess the prognostic relevance of elevated levels of S100A8 and S100A9 in breast cancer, we utilized a publicly available cohort of combined clinical microarray data containing response rates to various therapies." (PMID 34771752, 2021). "For example, high mRNA levels of S100A8 and S100A9 predict worse prognosis in the luminal A-type breast cancer, while increased levels of S100A10, S100P, and S100Z showed shorter OS in patients with the basal-like subtype." (PMID 32722137, 2020).
breast carcinoma (continued). "In contrast, S100A7, S100A8 and S100A9, all of which are co-amplified on chromosome 1q21.3 in breast cancer, have similar functions and work together to induce target protein phosphorylation." (PMID 32929353, 2020). "The binding of S100A8/S100A9 to RAGE promotes breast cancer cell growth by inducing MAPK signalling." (PMID 32722137, 2020). "The pro-inflammatory proteins S100A8/S100A9 are abundant in MDSC exosomes from breast cancer model mice and is chemotactic for MDSCs in vitro." (PMID 30792719, 2019). "Our results indicated that S100A9, S100A11 and S100P were associated with worse outcome in all breast cancer patients according to the Kaplan-Meier survival curves and the log-rank P value based on the database." (PMID 28051137, 2017). "Our results indicated that high mRNA expression of S100A8, S100A9, S100A11 and S100P were found to be significantly correlated to worse outcome, while S100A1 and S100A6 were associated with better prognosis in all breast cancer patients." (PMID 28051137, 2017). "S100A5, S100A6, S100A8 and S100A9 were correlated with prognosis in luminal A type breast cancer patients." (PMID 28051137, 2017). "Here, we show that primary human monocytes have a survival advantage, proliferate in vivo and develop into immunosuppressive myeloid cells expressing the myeloid-derived suppressor cell marker S100A9 only in a TN breast cancer environment." (PMID 27725631, 2016). "Suppressing S100A9 using inhibitor of DNA binding (1d1) promotes the migratory and invasive potentials of breast cancer." (PMID 26431492, 2015). "In breast cancer, S100A8 and S100A9 are also linked with tumor progression being involved in regulating cancer cell behavior through extracellular and intracellular signaling pathways." (PMID 25298751, 2014). "S100A9 expression is up-regulated in tumor cells in lung, prostate, and breast cancer, while it is down-regulated in human esophageal cancer cells." (PMID 22838504, 2012). "At the same time, in other cancer types, such as lung cancer, prostate cancer, and breast cancer, S100A9 is expressed mainly by neoplastic tumor cells themselves." (PMID 22838504, 2012). "In addition to modulating the tumor microenvironment and cell metabolism, S100A8/S100A9 enhances chemoresistance of breast cancer cells by activating pro-survival ERK1, ERK2 and ribosomal protein S6 kinas β1 pathways." (PMID 39830522, 2024). "Furthermore, S100A8 and S100A9 gene expression showed an ER-negative status in breast cancer patients." (PMID 39594999, 2024). "By overexpressing S100A9 in ER+breast cancer cells, we demonstrated that upregulating S100A9 could improve cocultured NK cell function." (PMID 38713229, 2024). "Additionally, the IHC staining also demonstrated that S100A8 and S100A9 were negatively correlated with DACH1 expression in breast cancer samples." (PMID 38093319, 2023). "In human breast cancer cells, S100a9 could promote autophagy and induce cell death by upregulating the expression of Beclin-1, as well as by promoting the formation of Atg12-Atg5 and lysosomal activation." (PMID 37723445, 2023). "Specifically for breast cancer, it is possible that S100A9-mediated immunosuppression enables the liver tropism of sEVHYP-exposed luminal cells, while also promoting mammary gland transformation via transcriptional coactivation of cancer genes and intercellular communication with transformed cells." (PMID 36892943, 2023). "Additionally, IHC staining assays were conducted with another TMA (HBre145Su01) to evaluate the expression of S100A9 in different molecular subtype breast cancers." (PMID 38093319, 2023). "In human breast cancer cells, S100a9 could promote autophagy by upregulating the Beclin-1 and promoting the formation of Atg12-Atg5 and lysosome activation, thereby inducing cell death." (PMID 37723445, 2023). "Despite its functional importance in breast cancer progression, the regulatory mechanism for S100A9 in TNBC cells is largely unknown." (PMID 35484101, 2022).
breast carcinoma (continued). "Thus, cancer-derived S100A9 in brain metastasis appears to be necessary and sufficient for radioresistance in experimental lung and breast cancer models." (PMID 35411077, 2022). "Three biomarkers, S100A8 (p-value = 0.0069, 7.8-fold increase), S100A9 (p-value = 0.0048, 10.2-fold increase), and Galectin-3 binding protein (p-value = 0.01, 3.0-fold increase) with an increased expression in breast cancer patients were selected for validation using ELISA." (PMID 35471994, 2022). "First, we confirmed the presence of S100A9+ cancer cells independently of the primary source of the metastasis; of note, the percentage was lower in melanoma brain metastases than in lung or breast cancer." (PMID 35411077, 2022). "Moreover, S100A9 can act as a transcriptional coactivator during breast cancer development and promotes the immune-suppressive activity of MDSCs." (PMID 36588678, 2022). "The S100A9-MCAM axis activates ETS translocation variant 4 (ETV4), which in turn transcriptionally upregulates ZEB1 to induce epithelial-mesenchymal transition and metastasis of breast cancer cells." (PMID 35484101, 2022). "Furthermore, S100A9 expression in human brain metastasis from patients with lung cancer, breast cancer or melanoma correlates with benefit from radiotherapy." (PMID 35411077, 2022). "It has been reported that S100A9 probably plays a key role in inflammation-related breast cancers and induces the expression of pro-inflammatory cytokines (IL-6, IL-8, and IL-1β), thus, its expression level can be used to diagnose breast cancer." (PMID 34490085, 2021). "Furthermore, S100A8 and S100A9 are upregulated in a variety of cancers such as lung cancer, prostate cancer, colon cancer, stomach cancer, and breast cancer." (PMID 34934042, 2021). "S100A8/S100A9 activates the MAPK pathway to promote the proliferation of breast cancer (BC)." (PMID 34712325, 2021). "Our results have shown that the serum level of S100A8/9 was significantly higher in patients vis-a-vis healthy controls, and this over-expression was positively correlated with tumor size, which is in line with the reported higher gene expression of S100A8 and S100A9 in breast cancer." (PMID 31528166, 2019). "Moreover, S100A8/S100A9 from mammary carcinoma cells bind to RAGE on MDSCs and promote the migration and accumulation of MDSCs through the NF-κB signaling pathways." (PMID 30792719, 2019). "Not unexpectedly, our results confirmed that S100A8 and S100A9 were significantly associated with lower OS for all breast cancer, especially in luminal A type, lymph node negative and grade 2 breast cancer patients." (PMID 28051137, 2017). "Recent experimental studies showed that exogenously added S100A8 and S100A9 proteins enhanced the proliferation of tumor cells such as breast cancer cells, colorectal and pancreatic cancer cells; the overexpression of intracellular S100A8 protein had a growth-promoting activity in keratinocytes." (PMID 28637501, 2017). "In addition, S100A8 and S100A9 enhance chemoresistance of breast cancer cells by activating the pro-survival ERK1, ERK2 and ribosomal protein S6 kinase β1 pathways." (PMID 28051137, 2017). "Instead, we could show that the DAMP, S100A9, also induced pro-inflammatory proteins in breast cancer cells expressing TLR4." (PMID 26392082, 2015). "Moreover, S100A8 and S100A9 seem to suppress breast cancer by activating mesenchymal to epithelial transition." (PMID 25298751, 2014). "Moreover, the production of S100A9 from breast cancer cells was quantified by ELISA." (PMID 38713229, 2024). "Furthermore, a significant (p < 0.05) positive correlation between ESR1 and S100A8 and S100A9 gene expression levels was observed in basal breast cancer patients; whereas such a correlation was significantly (p < 0.05) negative in the Her2, Luminal A, and Luminal B types of breast cancer patients." (PMID 39594999, 2024).